MIR6774 (microRNA 6774)
Synonyms: hsa-mir-6774
Gene: MicroRNA gene on chromosome 16 (85,918,347 to 85,918,416, forward strand). Ensembl gene ENSG00000274134.
Diseases named in the same sentence as MIR6774 in open-access papers:
MIR6774 is named in the same sentence as 1 disease in open-access papers, as found by Europe PMC text mining. Sharing a sentence is not in itself a finding about the gene and the disease. The quoted sentences say what the papers report.
cancer (1 paper, 2026). A tumor composed of atypical neoplastic, often pleomorphic cells that invade other tissues. "The role of MIR6774 gene in cancer mainly reflects the signal pathway that may participate in the regulation of cell proliferation and apoptosis, thus promoting malignant transformation and invasiveness of cancer cells." (PMID 41262533, 2026).